KCNN2 (potassium calcium-activated channel subfamily N member 2)
Diseases named in the same sentence as KCNN2 in open-access papers:
KCNN2 is named in the same sentence as 50 diseases in open-access papers, as found by Europe PMC text mining. Sharing a sentence is not in itself a finding about the gene and the disease. The quoted sentences say what the papers report.
Ataxia (6 papers, 2019 to 2025). Ataxia refers to impaired coordination of voluntary muscle movement. "This included two missense variants in KCNN2, with one (p.Leu611Ile) occurring de novo in a patient with infancy‐onset generalized myoclonus‐dystonia who also showed signs of bradykinesia and ataxia." (PMID 40533913, 2025). "The first had infancy‐onset generalized dystonia, myoclonus, ataxia, and bradykinesia—symptoms previously reported in KCNN2‐related disease —and carried a de novo variant, supporting its pathogenicity and confirming its role in myoclonus‐dystonia." (PMID 40533913, 2025). "All patients with pathogenic KCNN2 variants had motor and language developmental delay, intellectual disability often associated with early-onset movement disorders encompassing cerebellar ataxia, and/or extrapyramidal symptoms (NEDMAB OMIM 619725)." (PMID 37510285, 2023). "Using exome sequencing, a de novo KCNN2 frameshift deletion was identified in a patient with learning disabilities, cerebellar ataxia, and white matter abnormalities on brain MRI." (PMID 37510285, 2023).
Dystonia (6 papers, 2023 to 2026). An abnormally increased muscular tone that causes fixed abnormal postures. "In a 38-year-old woman and her 17-year-old daughter, both showing tremor, myoclonus, dystonia, and psychiatric symptoms, ES detected a heterozygous canonical splice-site c.1780-2A > G variant in KCNN2." (PMID 41982418, 2026). "This represents the first sufficient effect of GPi-DBS in a patient with a genetically confirmed KCNN2 mutation, highlighting its potential efficacy and underscoring the need for genetic testing in patients presenting with dystonia-myoclonus syndromes." (PMID 40869056, 2025). "Variants in KCNN2 were initially linked to neurodevelopmental disorders, sometimes with movement disorders, and later associated with tremulous myoclonus‐dystonia, We identified two patients with likely pathogenic missense variants." (PMID 40533913, 2025). "Screening our data for proposed dystonia candidate genes identified presumably pathogenic variants in CHD6, KCNN2, KLC1, NR4A2, and ZMYND11, but not in others, for example, ATP5F1B, ACBD6, CIZ1, SHQ1, and SPTBN1." (PMID 40533913, 2025). "In accordance with the scientific literature, we detected potentially relevant variations in known genes previously associated with CD and BSP, such as CIZ1, GNAL, and ANO3, and in other dystonia-related genes, such as KMT2B, VPS16, and KCNN2, for a total of nine patients." (PMID 37445923, 2023).
Anxiety (5 papers, 2011 to 2025). Intense feelings of nervousness, tension, or panic often arise in response to interpersonal stresses. "Kcnn2 overexpression in the amygdala reduces anxiety-like behavior, presumably by reducing amygdala output." (PMID 36163074, 2022). "PEBP1 has been suggested to be involved in chronic stress-induced memory impairment, MOBP has been linked to mood disorders, LTA4H to depression in women, and KCNN2 to anxiety and stress responses." (PMID 21504592, 2011). "In the mouse model of Angelman syndrome that shows motor learning deficit and anxiety similar to our mouse model of FASD, malfunction of the feedback regulation between NMDA and KCNN2 pathways was shown to lead to excessive KCNN2 at synapses and cause intellectual disabilities." (PMID 38734844, 2024).
Arrhythmia (4 papers, 2015 to 2018). Any cardiac rhythm other than the normal sinus rhythm. "The purpose of the present study was to test the association between KCNN2 common genetic variants and cardiac arrhythmias, including both VTa and AF." (PMID 27442679, 2016). "They suggested that the as the KCNN2 gene is highly expressed in arterial myocytes it might be associated with heart disease such as arrhythmias." (PMID 26434682, 2015).
atrial fibrillation (4 papers, 2018 to 2025). A disorder characterized by an electrocardiographic finding of a supraventricular arrhythmia characterized by the replacement of consistent P waves by rapid oscillations or fibrillatory waves that vary in size, shape and timing and are accompanied by an irregular ventricular response. "Nevertheless, given the associations of KCNN2 channel activity with conditions like atrial fibrillation and epilepsy, close monitoring of Lei-Dab7’s effects, especially on cardiac functions, will be imperative." (PMID 40795325, 2025). "Calcium-activated K+ via its specific channels promotes action potential (AP) repolarization; accordingly, some KCNN2 and KCNN3 variants are associated with increased atrial fibrillation (AF) risk." (PMID 37372431, 2023).
autism (3 papers, 2021 to 2025). Persistent deficits in social interaction and communication and interaction as well as a markedly restricted repertoire of activity and interest as well as repetitive patterns of behavior. "The Alternative Splice Site Predictor (ASSP) tool (Wang and Marín, 2006) determined short windows containing the loci for each of the GABBR1 and KCNN2 autism-associated genes." (PMID 33958984, 2021). "However, increased Kcnn2 decreased intrinsic excitability of cortical pyramidal neurons in a PTEN-associated autism mouse model." (PMID 39569070, 2024). "The autism-associated KCNN2 variant may either change the level of the baseline SK2 channel expression or lead to the alteration of the splicing, and the shift of the open reading frame." (PMID 33958984, 2021). "Because of the relative likelihood that autism-associated intron variants such as those found in GABBR1 and KCNN2 would result in transcriptomic changes, transcriptomics should be a primary focus of future research on these genetic variants’ impact." (PMID 33958984, 2021). "In that study, KCNN2, encoding for the voltage-independent Ca2+-activated K+ channel, was the most strongly associated gene with autism that did not contain any genome-wide significant SNP." (PMID 39905010, 2025). "The autism-associated GABBR1 and KCNN2 genetic variants have been highlighted as such only recently, and therefore there is an opportunity to collect more definitive experimental data, which can inform the modeling of sensory processing dynamics as they relate to these variants." (PMID 33958984, 2021).
Cognitive impairment (3 papers, 2022 to 2025). Abnormal cognition is characterized by deficits in thinking, reasoning, or remembering. "Our study explores the therapeutic potential of postnatal KCNN2 blockade for cognitive deficits in FASD." (PMID 40795325, 2025). "On the whole, it is posited that KCNN2 is crucial in the regulation of neural networks in sleep and may also be altered during OSA-induced cognitive impairment and other neurological injuries." (PMID 36245838, 2022).
Intellectual disability (3 papers, 2023 to 2024). "The genetic variants in KCNN2 were found in individuals with intellectual disability, developmental motor and language delays, and movement disorders." (PMID 39202429, 2024).
Angelman syndrome (2 papers, 2024 to 2025). A neurogenetic disorder characterized by severe intellectual deficit and distinct facial dysmorphic features. "Taken together, our findings advocate for the therapeutic potential of Lei-Dab7 or other KCNN2 blockers for FASD and possibly other neurodevelopmental diseases that similarly involve KCNN2 upregulation, such as Angelman syndrome." (PMID 40795325, 2025). "Studies using mouse models have shown that pharmacological blockade of KCNN2 channels may offer therapeutic effects for conditions such as fetal alcohol spectrum disorders (FASD) and Angelman syndrome." (PMID 40795325, 2025).
Ewing sarcoma (2 papers, 2012 to 2019). A small round cell tumor that lacks morphologic, immunohistochemical, and electron microscopic evidence of neuroectodermal differentiation. "The expression of the selected target genes in Ewing’s sarcoma (CAV1, NR0B1, IGFBP3 and TGFBR2), together with the expression of HIST1H4L, KCNN2, ECRG4 and LDOC1, was then validated in an independent series of PCa with and without ETS gene fusions, as well as in a series of ESFT and ARMS." (PMID 23185447, 2012).
glioma (2 papers, 2012 to 2026). A benign or malignant brain and spinal cord tumor that arises from glial cells (astrocytes, oligodendrocytes, ependymal cells). "KCNN2 expression has been previously reported in human glioma, and in melanoma KCNN2 is thought to help regulate hypoxia-induced cell proliferation." (PMID 22937035, 2012).
heart failure (2 papers, 2016 to 2019). Inability of the heart to pump blood at an adequate rate to meet tissue metabolic requirements. "There was also trends toward decreased transcription of KCa2.2 (Kcnn2) and increased transcription of adrenergic receptor subtype Adra1d, thought to protect against pathological remodeling in heart failure." (PMID 31068841, 2019).
melanoma (2 papers, 2012 to 2019). A malignant, usually aggressive tumor composed of atypical, neoplastic melanocytes. "By in vitro experiments, one gene (namely: KCNN2) has been validated as a relevant molecular target in melanoma cell lines." (PMID 30934896, 2019). "Such five genes (namely, SCNN1A, GJB3, KCNK7, GJB1, KCNN2) are novel potential melanoma markers or molecular targets, never previously related to melanoma." (PMID 30934896, 2019). "Five such genes (namely: SCNN1A, GJB3, KCNK7, GJB1, KCNN2) were identified as potential strong melanoma markers that had never been identified before." (PMID 30934896, 2019).
schizophrenia (2 papers, 2017 to 2023). A major psychotic disorder characterized by abnormalities in the perception or expression of reality. "The KCNN2-Aβ40TX locus was also associated with age of onset for AD, epistatic interactions with amyloid, schizophrenia, bipolar disorder and hippocampal sclerosis." (PMID 36609403, 2023).
Ventricular arrhythmia (2 papers, 2016 to 2024). "Variants of the KCNN2 gene are associated with the occurrence of lethal ventricular arrhythmias in patients with underlying heart diseases." (PMID 27442679, 2016). "The beneficial effect on ventricular arrhythmias may be attributed to a direct pharmacological effect of sacubitril/valsartan on cardiac reverse remodeling and/or small-conductance Ca2+-activated potassium channel type 2 (KCNN2)-associated electrical remodeling." (PMID 39749312, 2024).
cardiac hypertrophy (1 paper, 2022). "The abnormal expression of KCNN2 after cardiac hypertrophy may be related to some important heart process." (PMID 35953789, 2022). "Taken together, these results indicate that m6A modification may promotes KCNN2 and BMP4 mRNA stability when mice develop cardiac hypertrophy." (PMID 35953789, 2022). "Both KCNN2 and BMP4 have been confirmed to play essential roles in cardiac hypertrophy." (PMID 35953789, 2022).
cervical dystonia (1 paper, 2025). "The second variant (p.Ser376Leu), located in the protein's highly missense‐intolerant ion channel domain which harbors other pathogenic variants, was found in a patient with isolated cervical dystonia since age 27 years, potentially broadening the phenotypic spectrum of KCNN2." (PMID 40533913, 2025).
endothelial dysfunction (1 paper, 2023). In vascular diseases, endothelial dysfunction is a systemic pathological state of the endothelium (the inner lining of blood vessels) and can be broadly defined as an imbalance between vasodilating and vasoconstricting substances produced by (or acting on) the endothelium. "Similarly, abnormalities within the KCNN2 gene, which encodes a calcium-dependent potassium channel, can be linked to endothelial dysfunction, but the detailed mechanism of the influence that circRNAs derived from these genes have over specific pathobiological states has not yet been demonstrated." (PMID 37373172, 2023).
glioblastoma (1 paper, 2025). The most malignant astrocytic tumor (WHO grade IV). "Glioblastoma studies included E5 (KCNJ10, KCNN3), E21 (KCNAB2), E26 (KCNE2, KCNJ13), E27 (KCNE4, KCNMB2-AS1), E31 (KCNJ10), E50 (KCND3), and E51 (KCNIP1, KCNJ16, KCNN2)." (PMID 40867621, 2025).
Kyphosis (1 paper, 2010). Exaggerated anterior convexity of the thoracic vertebral column. "SNPs in KCNN2 on SSC2, RYR1 and PLOD1 on SSC6 and MYST4 on SSC14 were significantly associated with kyphosis in the resource population of swine (P ≤ 0.05)." (PMID 21176156, 2010).
rectum tumor (1 paper, 2019). "However, only the TCGA dataset contained rectum tumor samples, in which the expression profiles of KCNN2, STIM2 and TRPM6 followed that of the distal tumor samples." (PMID 31010205, 2019).
serous ovarian cancer (1 paper, 2024). "Thus, high KCNN2 mRNA level could be associated with a better outcome from chemotherapy treatment in the early stages of serous ovarian cancer, but the benefits were lost in more advanced forms of the disease." (PMID 38480668, 2024). "To explore the clinical relevance of KCNN2 expression level on the progression‐free survival of patients with serous ovarian cancer, we used the Kaplan–Meier plotter database." (PMID 38480668, 2024). "Additionally, SK2 activity increases chemotherapy efficacy and KCNN2 expression levels may constitute a prognostic marker for early stages of serous ovarian cancer." (PMID 38480668, 2024). "Furthermore, we discovered that plasma membrane SK2 inhibition increased chemoresistance to Taxol® and that KCNN2 mRNA expression level may constitute a prognostic marker for early stages of serous ovarian cancer." (PMID 38480668, 2024).
tumor (6 papers, 2017 to 2024). "GABA receptor signaling pathway enrichment was defined by elevated expression of GABRB3 and potassium channel genes, KCNN1, KCNN2, and KCNQ3, and decreased expression of ADCY2, which have all been indicated as important in tumor growth (32, –, 34)." (PMID 28049147, 2017). "KCNN2 significantly decreased in HCC tissues, suggesting the parental gene of circKCNN2 may also act as a tumor suppressor in HCC." (PMID 35051313, 2022). "Interestingly, expression levels of HERC3, KCNN2, and MRPL52 were not significantly varied in tumor group and control group." (PMID 38918720, 2024).
cancer (5 papers, 2014 to 2024). A tumor composed of atypical neoplastic, often pleomorphic cells that invade other tissues. "In cancer cells, KCNN2 and KCNN4 activity triggers their migration." (PMID 39716493, 2024). "Since KCNN2 is important for mediating the increase of transepithelial secretion in biliary epithelial cells and prominently expressed in intact liver, it seems some function of normal liver was gradually suppressed in pericancerous and cancer liver." (PMID 24564407, 2014). "On the contrary, KCNN2 was down-regulated in pericancerous and more down-regulated in cancer liver." (PMID 24564407, 2014). "Thus, mRNA levels of KCNN2 and KCNN3 channels may constitute a promising prognostic marker or interesting targets to regulate chemosensitivity of several cancers." (PMID 38480668, 2024).
movement disorder (5 papers, 2022 to 2025). Neurological conditions resulting in abnormal voluntary or involuntary movement, which may impact the speed, fluency, quality and ease of movement. "The variation in KCNN2 is related to movement disorders in rodents and humans." (PMID 36670743, 2023).
neurodevelopmental disorder (4 papers, 2023 to 2025). A behavioral and cognitive disorder with onset during the developmental period that involves impaired or aberrant development of intellectual, motor, or social functions. "This study focused on the genetic cause triggering ID in the 5q region, identifying KCNN2 as the most plausible gene due to the association with a neurodevelopmental disorder accompanied by behavioral abnormalities, with a possible mechanism of haploinsufficiency." (PMID 37510409, 2023).
neurological diseases (1 paper, 2023). "Variants in the KCNN2 gene have been recently associated with neurological diseases." (PMID 37510285, 2023).
KCNN2 also shares sentences with these, for which no sentence is quoted: Myoclonus (4 papers); Tremor (4); epilepsy (3); heart disease (3); cardiac arrhythmias (2); cerebellar ataxia (2); essential tremor (2); alveolar rhabdomyosarcoma (1); Alzheimer disease (1); aneurysm (1); cholangiocarcinoma (1); depression (1); development delay (1); diabetes (1); generalized dystonia (1); genetic generalized epilepsy (1); hyperlipidaemia (1); learning disabilities (1); memory impairment (1); mood disorder (1); Parkinsonism (1); sarcoma (1); spinocerebellar ataxia 3 (1).